HEY2 (hes related family bHLH transcription factor with YRPW motif 2)
Diseases named in the same sentence as HEY2 in open-access papers (continued):
Sharing a sentence is not in itself a finding about the gene and the disease.
endometrial cancer (3 papers, 2013 to 2022). Primary or metastatic malignant neoplasm involving the endometrium (mucous membrane that lines the endometrial cavity). "Although these data did not support the candidate susceptibility gene HEY2, bioinformatic analysis has previously suggested its targeting by endometrial cancer GWAS risk variation." (PMID 34675350, 2021). "The associations of CYP19A1, SKAP1, HEY2, EEFSEC, and EVI2A were supported by colocalization of eQTL and GWAS signals in at least one of the relevant tissues; thus, these five genes were prioritized as candidate endometrial cancer susceptibility genes." (PMID 34675350, 2021). "All EpiMods demonstrated strong enrichment for biological terms, with the HAND2 EpiMod itself highly enriched for other transcription factors (e.g., GATA4, HEY2, HOXD13, PHOX2A, HAND1), all of which were also hypermethylated in endometrial cancer." (PMID 24265601, 2013).
oligodendroglioma (3 papers, 2018 to 2022). A well-differentiated (WHO grade II), diffusely infiltrating neuroglial tumor, typically located in the cerebral hemispheres. "For example, reduced expression of Notch targets, namely HES1, HEY1, and especially HEY2, was seen in clinically progressed oligodendroglioma, while HES5 expression was most associated with shorter survival on multivariable analysis." (PMID 30417117, 2018).
ovarian carcinoma (3 papers, 2018 to 2021). A malignant neoplasm originating from the surface ovarian epithelium. "Causal network analysis revealed novel pathways suggesting predicted inhibition of ovarian cancer through master regulator ASCL1 and dataset genes DCX, SEMA6B, HEY2, and KCNIP2." (PMID 35052372, 2021).
adenoma (2 papers, 2017 to 2020). A neoplasm arising from the epithelium. "Notch target genes, Hes1, Hes5, Hey1, and Hey2, were upregulated ≥2-fold in 33%, 31%, 24%, and 32% of CRCs, respectively, whereas in adenomas, they were overexpressed in 22%, 22%, 11%, and 11%, respectively." (PMID 32211044, 2020). "KrasG12D upregulates expressions of Notch2, Notch3, Notch4, Jag1 and downstream target genes Hes1, Hey1 and Hey2, and deletion of Jag1 partially suppresses KrasG12D-induced adenoma development." (PMID 29142904, 2017).
congenital heart defects (2 papers, 2021 to 2025). "Germline variants in HEY2 have been linked to congenital heart defects and thoracic aneurysms, underscoring the interdependence between early developmental patterning and adult aortic wall remodeling." (PMID 40981152, 2025). "Variants in HEY2 have been associated with both congenital heart disease and thoracic aneurysms, highlighting its dual role in cardiovascular morphogenesis and adult aortic remodeling." (PMID 40981152, 2025). "Germline variants in HEY2 have been associated with both congenital heart disease and thoracic aortic aneurysms, suggesting a shared developmental etiology." (PMID 40981152, 2025).
migraine (2 papers, 2022 to 2023). "One genome-wide significant lead SNP (rs10457469, near HEY2) from the cross-trait meta-analysis of migraine and T2D was not novel as, although it was genome-wide suggestive in the individual migraine GWAS, it was genome-wide significant in the individual T2D GWAS." (PMID 36292730, 2022).
prostate carcinoma (2 papers, 2016 to 2024). A carcinoma that arises from epithelial cells of the prostate gland. "Furthermore, high expression of HEY2 in prostate cancer was associated with poor survival and served as an independent prognostic factor." (PMID 27191260, 2016).
radiation proctitis (2 papers, 2017 to 2023). "Total body irradiation and radiation proctitis were monitored to investigate the impact of conditional Hey2 deletion on intestinal stem cells and microvascular compartment radiosensitivity, EndoMT and rectal damage severity." (PMID 28694461, 2017). "In this study we show that conditional deletion of Hey2 in the endothelial compartment reduces EndoMT frequency and the severity of radiation proctitis." (PMID 28694461, 2017). "In radiation proctitis, endothelial cell-specific knockout of Hey2 may protect the endothelial and the epithelial cell compartment from radiation damage." (PMID 36915092, 2023). "Because transfection by itself may have deleterious effects and does not represent what happens in vivo, we decided to investigate the involvement of Hey2 in radiation-induced EndoMT in our preclinical model of radiation proctitis in mice." (PMID 28694461, 2017). "The first step was to investigate whether Hey2 deletion in endothelial cells lessened radiation-induced EndoMT in our preclinical model of radiation proctitis." (PMID 28694461, 2017). "Given that Hey2 deletion in the endothelial compartment lessened acute radiation proctitis, we aimed to determine whether this has an impact on late rectal injury." (PMID 28694461, 2017).
Tetralogy of Fallot (2 papers, 2018 to 2019). A congenital cardiac malformation comprising pulmonary stenosis, overriding aorta, ventricular septum defect, and right ventricular hypertrophy. "The inactivation of Hey2, a significant Notch signaling molecule, in mice resulted in a spectrum of cardiac malformations that resembled those associated with mutations of human JAG1, associated with Tetralogy of Fallot (TOF), VSD, and tricuspid atresia." (PMID 30897084, 2019). "Similarly, Hey2 knockout mice display defects including atrioventricular valvular defects, pulmonary stenosis, Tetralogy of Fallot, tricuspid atresia, and abnormal cardiac hemodynamics, indicating that Hey2 is an essential regulator of cardiac morphogenesis and cardiac function." (PMID 29422515, 2018). "The expression of Hey2 in the endocardial cells of the AVC and OFT and mesenchymal cells derived from those endocardial cells might explain the atrioventricular valve defects, pulmonary stenosis, tetralogy of Fallot, and tricuspid atresia found in the Hey2 knockout mice." (PMID 29422515, 2018).
anemia (1 paper, 2010). A reduction in the number of red blood cells, the amount of hemoglobin, and/or the volume of packed red blood cells. "Hey2 mRNA is induced by hypoxia so this down-regulation of Hey2 mRNA is again consistent with the absence of anemia in garlic-fed mice." (PMID 21206920, 2010).
atherosclerosis (1 paper, 2022). A disease characterized by the build-up of fatty material and calcium deposition in the arterial wall resulting in partial or complete occlusion of the arterial lumen. "Other potential markers including HEY2 (identified by sensitivity analysis) and PECAM1 (identified by MR and sensitivity analysis) and the top causal pairs BIRC2–PLOD1 and CRBN–MRPL40 also suggested a role of immunity in atherosclerosis." (PMID 35706446, 2022).
biliary atresia (1 paper, 2020). A rare, biliary tract disease characterized by progressive obliterative cholangiopathy of the intra- and extrahepatic bile ducts, occurring in the embryonic/ perinatal period, leading to severe and persistent neonatal jaundice and acholic stool. "Biopsies of patients with biliary atresia demonstrated increased RhoU/Wrch1 and Hey2 expression in cholangiocytes." (PMID 32371929, 2020).
cardiac arrest (1 paper, 2018). Cessation of breathing and/or cardiac function. "The rs9388451 genetic locus adjacent to the HEY2 gene was associated with cardiac arrest/VF in an analysis using the UK Biobank study (odds ratio = 1.13 (95% confidence interval: 1.08–1.18), P = 0.006)." (PMID 30042696, 2018). "The association of the HEY2 loci with cardiac arrest/VF is obviously very interesting but the association needs to be replicated when an independent dataset of similar size becomes available." (PMID 30042696, 2018). "In order to investigate a similar general population, we used 382,000 white British participants from UK Biobank, and found the HEY2 risk allele rs9388451 to associate with cardiac arrest/VF, indicating a potential lethal effect of the common genetic variant." (PMID 30042696, 2018). "Furthermore, the HEY2 risk allele was associated with cardiac arrest/VF in a similar general population of the United Kingdom, indicating a potential lethal effect of the common genetic variant." (PMID 30042696, 2018).
Cirrhosis (1 paper, 2017). A chronic disorder of the liver in which liver tissue becomes scarred and is partially replaced by regenerative nodules and fibrotic tissue resulting in loss of liver function. "Yet, we observed that Jag1, Notch 1, Notch 2, Notch 3, and Hey2 were significantly upregulated in both Ep+CIR and Ep+HCC cells as compared to Ep+NSCs, indicating the appearance of CSC like phenotype during advanced cirrhosis." (PMID 28176469, 2017).
Cognitive impairment (1 paper, 2025). Abnormal cognition is characterized by deficits in thinking, reasoning, or remembering. "Individuals with chromosomal deletion of HEY2 exhibit cardiac defects and cognitive impairment, and duplication of HEY2 leads to congenital heart defects and neurodevelopmental delays." (PMID 41459558, 2025).
colon cancer (1 paper, 2023). "For instance, a previous study concluded that colon cancer cells with DDR1 overexpression have the ability to survive more due to the activation of Notch1 which stimulates the expression of pro-survival genes Hes1 and Hey2." (PMID 37271822, 2023).
colorectal adenoma (1 paper, 2020). An adenoma that arises from the colon or rectum. "We investigated mRNA expression of four Notch receptors (Notch1–4), five ligands (Jag1, Jag2, Dll1, Dll3, and Dll4), and four target genes (Hes1, Hes5, Hey1, and Hey2) using highly specific TaqMan gene expression assays in colorectal adenomas and cancers." (PMID 32211044, 2020).
colorectal tumor (1 paper, 2023). "Elevated Hey2, Jag1 and Notch1 expression was also observed in whole sWAT fat pads during cachexia in C26 colorectal tumor-bearing mice, showing that this genetic program is not restricted to PDAC." (PMID 37749321, 2023).
deafness (1 paper, 2017). An inherited or acquired condition characterized by the complete loss of the ability to hear from one or both ears. "Results of previous studies provide evidence that HEY2 regulates the differentiation of mammalian auditory hair cells, whereas SLC16A6 is expressed in cochlear sensory hair cells and plays a role in deafness." (PMID 28097054, 2017).
gastric cancer (1 paper, 2016). A primary or metastatic malignant neoplasm involving the stomach. "HEY2 increase induced by Notch activation contributed to the acquisition of chemoresistance in gastric cancer." (PMID 27191260, 2016).
human papillomavirus infection (1 paper, 2024). "KEGG enrichment analysis revealed that HEY2 is involved in the human papillomavirus infection and Notch signaling pathways, both of which play significant roles in the development and progression of HNCs." (PMID 39684225, 2024).
infantile hemangiomas (1 paper, 2011). "After analysis of eight members of the HES/HEY family, we found that HES1, HEY1, HEY2 and HEYL are expressed in infantile hemangiomas." (PMID 21834989, 2011).
insulinomas (1 paper, 2010). "Relative to Dll4+/+ insulinomas, Dll4+/- tumors showed an approximately 50% reduction in Dll4 mRNA levels, as expected, as well as reduced Hey2 expression, consistent with a reduction in Notch signaling." (PMID 21092311, 2010).
mucinous tumors (1 paper, 2021). "In contrast to non‐mucinous tumors, the mucinous tumors from KLN mice displayed significant up‐regulation of Notch pathway components including Hes1, Hes5, Hey1 and Hey2, but not Wnt nor Hedgehog signaling." (PMID 33439550, 2021).
Osteopenia (1 paper, 2021). Osteopenia is a term to define bone density that is not normal but also not as low as osteoporosis. "Conversely, as a negative regulator, suppressing HEY2 with Notch2 antisense oligonucleotides (ASO) attenuated the cancellous osteopenia of Notch2tm1.1Ecan mice." (PMID 35003523, 2021).
papillary thyroid carcinoma (1 paper, 2021). "miR‐599 promotes apoptosis in papillary thyroid carcinoma cells by targeting Hey2, which is a transcription factor involved in cell fate and forming boundary." (PMID 33205602, 2021).
papilloma (1 paper, 2017). A benign epithelial neoplasm that projects above the surrounding epithelial surface and consists of villous or arborescent outgrowths of fibrovascular stroma. "Compared to D4BE papillomas, D4OE tumors had on average 2.8-fold increased Dll4 mRNA levels and 2.5-fold up-regulated Hey2 transcription confirming the Dll4/Notch pathway over-induction." (PMID 28288569, 2017).
prolactinoma (1 paper, 2017). "Additionally, we show that Notch target gene Hes1 and Hey2 levels were decreased in prolactinoma cell lines, in line with a previous finding in human prolactinomas, while on the contrary, Hey1 was overexpressed in GH3 cells." (PMID 28915655, 2017).
renal clear cell carcinoma (1 paper, 2022). "Moreover, the overexpression of Notch1 intracellular segment in VHL knockout mice revealed accumulation of intracellular fat, cytoplasmic dysplasia nests, and upregulated expression of Hey1 and Hey2 downstream of the Notch pathway, similar to human renal clear cell carcinoma." (PMID 35096263, 2022).
tumor (20 papers, 2015 to 2025). "In the present study, HEY2 expression was associated with tumor differentiation." (PMID 27191260, 2016). "Because HEY2 expression was elevated in the follow-up biopsies compared with that in BCC debulk tissue, we next assessed the protein levels of NICD and HEY2 in the superficial debulk tumor, deep debulk tumor, and follow-up biopsies." (PMID 39086988, 2024). "In NSCLC, lncRNA PRNCR1 upregulates HEY2 promoting tumour progression by competitively binding miR-448." (PMID 32564237, 2020). "In the subgroups (tumor size, AFP level, tumor differentiation, TNM stage), HEY2 expression was reversely associated with the survival of post-resection HCC patients." (PMID 27191260, 2016). "High HEY2 expression was closely correlated with tumor multiplicity, tumor differentiation and TNM stage." (PMID 27191260, 2016). "High HEY2 expression was significantly correlated with advanced stage and poor tumor differentiation." (PMID 27191260, 2016). "Patients with high HEY2 expression were usually companied with multiple (P=0.017), poorly differentiated (P=0.019), and advanced-stage (P=0.006) tumor." (PMID 27191260, 2016). "Notably, miR-181b-5p and miR-877-5p acted as negative regulators of tumor-suppressor genes (e.g., HEY2, MCL2, HAND2), while miR-204-5p and miR-143-3p appeared to indirectly target oncogenes (e.g., RAB10, DR1, PTBP3, NCBP1)." (PMID 41009685, 2025). "Similarly, immunoblot analysis of HEY2 demonstrated elevated or persistent levels of HEY2 in the follow-up biopsies from all 4 patients compared with those in their matched superficial tumor tissue." (PMID 39086988, 2024). "The expression of Notch-1, Jagged-1, Hes-1 and Hey-2 was upregulated in OS tumor tissues." (PMID 33411691, 2020). "However, Notch-2, Jagged-1, Hey-1, and Hey-2 were overexpressed in OS tumor biopsy specimens, while Notch-1 and DLL1 were decreased in these specimens." (PMID 33411691, 2020). "We further studied whether Notch activation by the conditioned medium from normoxic or hypoxic MCF7 cells was dependent on gal-3 carbohydrate-binding domain and found that tumor-released gal-3 activates the Notch target HEY2 in a lactose inhibitable manner." (PMID 28533486, 2017). "Interestingly, DLL4 and Hey2 mRNA both had a 20-fold change difference in expression between the two tumor types." (PMID 28659656, 2017). "On the other hand, Notch target genes Hes1, Hes5 and Hey2 were expressed with a particular pattern for each gene, with higher Hes1 expression in tumor corticotropes and reduced Hes5 and Hey2 mRNA levels compared with normal pituitary glands, Hey2 being almost undetectable in ATt20 cells." (PMID 28915655, 2017). "Additionally, analysis of the expression of the target genes Hes1, Hey1 and Hey2 suggested variable activation which differed substantially between clonal cell lines, tumor xenografts and normal pituitaries." (PMID 28915655, 2017). "The hypoxia-Notch gene subset (HIF-1α/PGK1/VEGF/CA9/OPN-Notch1/Dll1/Hes1/Hes6/Hey1/Hey2) identified by us might hold prognostic implication and offer new opportunities in tumor sub-classification and targeted therapy." (PMID 25734817, 2015). "However, overall, it is apparent that hypoxic gliomaspheres mimic the in-vivo tumor condition better than the other tissue culture model as the upregulation of Notch genes (Notch1, Notch2, Notch3, Dll1, Hes1, Hey1 and Hey2) is further enhanced upon exposure to hypoxia." (PMID 25734817, 2015). "In obese EA patients, enriched pathways were dominated by extra-nuclear estrogen signaling (e.g., ESR1, ESR2, HEY2, MCL1), suggesting a strong hormonal component in TNBC tumor biology." (PMID 41009685, 2025). "As expected, HES1, HEY2, N-cadherin, and Vimentin expression was increased, and E-cadherin expression was decreased in MDA-MB-231 tumor with BEND5 knockdown." (PMID 35844785, 2022).
tumor (continued). "Univariate analyses indicated HEY2, as well as tumor size, AFP, tumor capsule, TNM stage, vascular invasion, lymph node metastasis and tumor differentiation, served as a prognostic factor in HCC." (PMID 27191260, 2016). "Strikingly, CD31+ cells from HT29-LAMA5sh tumours demonstrated the increased expression of several Notch pathway genes including Hey2; an essential downstream target of Notch and mediator of Notch signalling." (PMID 31064120, 2019). "Patients expressing less HEY2 survived longer (P=0.003) and experienced a longer period without tumor progression (P=0.008)." (PMID 27191260, 2016). "Similar to NICD, HEY2 did not localize to a particular basal or suprabasal tumor compartment." (PMID 39086988, 2024). "Finally, loss of Notch1 in tumor cells did not affect the protein expression of Notch2, Jag1, and BEC marker Sox9 as well as mRNA levels of Notch targets, including Hes5 and Hey2." (PMID 29545603, 2018).
cancer (14 papers, 2015 to 2025). A tumor composed of atypical neoplastic, often pleomorphic cells that invade other tissues. "Specifically, HEY2 has been implicated in the progression of various human cancers." (PMID 39684225, 2024). "HEY2, a bHLH transcription factor, has been implicated in the progression of human cancers." (PMID 27191260, 2016). "Some of these genes are reported in other cancer-implicated signaling pathways such as Ras (SPON1), SHH (SMO), and Notch (HEY2)." (PMID 39620202, 2024). "The interactions of HEY2 with Stat3 and Id4 that play important roles in tumorigenesis, also confirm the oncogenic role of HEY2 in human cancers." (PMID 27191260, 2016). "HEY2 was revealed as a direct target of miR-137 that is frequently downregulated in human cancers including HCC." (PMID 27191260, 2016). "In luminal A cancer, low expression of CTBP1, HEY1, HEY2 was associated with worse OS." (PMID 41463075, 2025). "In human cancers, HEY2 overexpression exerts pro-oncogenic activities." (PMID 27191260, 2016). "The level of APH1A, CTBP1, HEY1, HEY2, JAG2, NOTCH4 was significantly higher in cancer samples compared to the control group, while the concentration of DTX1 TLE2, TLE4 was below the detection threshold." (PMID 41463075, 2025). "Other Notch targets (HEY1, HEY2 and HES4) also exhibited increased transcript levels in cancer cells compared to benign prostate cells, though the differences in expression were less dramatic than that observed for HES6." (PMID 25864518, 2015). "Present data show that NILCO molecules (Notch1, Notch2, Notch3, Notch4, DLL4, and JAG1) and targets (Survivin, Hey2, IL-1R tI, and OB-R) were expressed in EmCa regardless of ethnicity and cancer type." (PMID 28659656, 2017). "Analysis revealed overexpression of APH1A, CTBP1, HEY1, HEY2, JAG2, NOTCH4 regardless of the cancer subtype." (PMID 41463075, 2025).